RNU6-475P (RNA, U6 small nuclear 475, pseudogene)
Gene: Small nuclear RNA gene on chromosome 6 (114,866,873 to 114,866,976, reverse strand). Ensembl gene ENSG00000251882.
Homologues: Orthologues: chimpanzee U6 (100% identical), macaque U6 (96% identical), rat LOC120103233 (62% identical). Paralogues in human: RNU6-1083P (78% identical), RNU6-1181P (78% identical), RNU6-1067P (77% identical), RNU6-16P (77% identical), RNU6-429P (77% identical), RNU6-74P (77% identical), RNU6-926P (77% identical), RNU6-106P (76% identical), RNU6-1152P (76% identical), RNU6-1251P (76% identical), RNU6-338P (76% identical), RNU6-500P (76% identical), and 1284 more.